IL4 (interleukin 4)
Diseases named in the same sentence as IL4 in open-access papers (continued):
Sharing a sentence is not in itself a finding about the gene and the disease.
allergic rhinitis (continued). "IL-4, IL-5, and IL-13 are produced by TH2 type cells and have cardinal roles in allergic rhinitis." (PMID 31807241, 2019). "Furthermore, the results showed that coptisine suppressed OVA-induced allergic rhinitis symptoms, such as nasal rubbing and OVA-specific IgE, and histamine, IL-4 and TNF-α levels in the serum of AR mice." (PMID 30469322, 2018). "Allergic rhinitis and chronic rhinosinusitis with polyposis are examples of persistent inflammatory diseases of the upper airway dominated by CD4+ Th2 effector cells secreting IL-4, IL-5, and IL-13 in response to commonly inhaled antigens." (PMID 25090641, 2014). "SST may also suppress IL-4 production in CD4+ T cells by influencing CD28-CD86 interactions and may correct a Th2-dominant condition in allergic rhinitis." (PMID 24324897, 2013). "Shikonin has been shown to alleviate excessive Th2 cell activation in rat models of allergic rhinitis by reducing the expression of co-stimulatory molecules CD80 and CD86 on dendritic cells while concurrently reducing the circulating levels of IL-4 in peripheral blood." (PMID 41560747, 2025). "There was no IL-4 and IL-5 production in the patients, which was expected as both cytokines are typical messengers for type 1 allergic reactions (immediate reaction, e.g. hay fever, allergic rhinitis)." (PMID 35147719, 2023). "OVA-specific IgE was decreased significantly in a dose-dependent manner after GA treatment in an allergic rhinitis mouse model, which may be induced by inhibiting TH2 cell differentiation and maturation, and IL-4 production subsequently prevented allergic rhinitis development." (PMID 28775294, 2017). "In another study, the intake of DSW has reduced allergic skin responses and serum levels of total IgE, Japanese cedar pollen-specific IgE, interleukin-4 (IL-4), IL-6, IL-13, and IL-18 in the patients with allergic rhinitis, compared to the distilled water intake which fails to give those effects." (PMID 28105060, 2016).
pulmonary fibrosis (137 papers, 2005 to 2026). Chronic progressive interstitial lung disorder characterized by the replacement of the lung tissue by connective tissue, leading to progressive dyspnea, respiratory failure, or right heart failure. "The bipartite APNet graph contained a large community connecting several drivers (IL6–JUN–CCL7–MAPK9–POLR2F–HSPA1A–BAX–TRIAP1), associated with interleukin signalling (IL4/13/17/18), cytokine stimulation, liver disease, and lung fibrosis." (PMID 39921901, 2025). "Other important mediators associated with lung fibrosis are legumain, osteopontin, IL-4, IL-6, IL-13, IL-17, TNF-α, Gal-1, Gal-3, PDGF, and FGFR-1." (PMID 38540252, 2024). "Previous studies showed that bleomycin–induced lung fibrosis was diminished in mice deficient in IL-13, IL-4 and their downstream transcription factor STAT6 or treated with a neutralizing anti–IL-13 antibody." (PMID 29782549, 2018). "In vitro, IL-4 promotes excess extracellular matrix production, and Th2 cytokines in vivo are associated with increased lung fibrosis in SSc." (PMID 16879746, 2006). "Enhanced production of IL-4 has also been observed in pulmonary fibrosis associated with systemic sclerosis, which also exhibits a lower Th2/Th1 ratio than UIP, and further is associated with a substantially higher level of INFγ production in tissue." (PMID 16287509, 2005). "Gene polymorphism involving inflammatory regulators may be associated with pulmonary fibrosis, which includes IL-1RN, IL-4, Toll-like receptor 3, and TOLLIP (Toll-interacting protein) among others." (PMID 40124525, 2025). "In pulmonary fibrosis, IL-4 can have functions like it may cause lung fibroblasts to express the collagen gene and encourage fibroblast differentiation." (PMID 38420070, 2024). "In this study, IL-4 deficient mice developed significantly less pulmonary fibrosis than wt mice." (PMID 34737752, 2021). "Increased IL-4 expression has been linked to pulmonary fibrosis." (PMID 34737752, 2021). "It has been shown that in severe lung fibrosis mice, the degree of pulmonary fibrosis was more alleviated in IL-4 knockout mice compared to normal mice." (PMID 40433386, 2025). "Previous studies have confirmed that Th2 cytokines play a leading role in pulmonary fibrosis, and its pathogenesis is related to the secretion of IL-4, IL-5 and IL-13." (PMID 39346776, 2024). "In controlled experiments of clinical treatment, the expression levels of IL-13, IL-4, IL-13Rα2, and IL-13-induced target genes were found to be significantly higher in lung tissues of idiopathic pulmonary fibrosis compared with controls." (PMID 38890719, 2024). "Research conducted by Ying-Wei Lan showed that, compared with mice with induced pulmonary fibrosis, the group treated with Kefir yogurt showed a notable downregulation of pro-inflammatory factors such as IL-4, IL-6, and TNF-α." (PMID 39683559, 2024). "We also observed a significant increase in IL-4 and IL-13 levels in plasma in ES silicotic patients, both cytokines are mainly associated with the TH2 response and associated with inflammation and lung fibrosis." (PMID 36675056, 2023). "Th2 cells, regulated by the GATA-binding protein 3 (GATA3), can secrete interleukin-4 (IL-4) and promote pulmonary fibrosis in the later fibrotic stage." (PMID 37828528, 2023). "There was found a significant increase in the BAL fluid levels of IL-4, IL-6, IL-7, and IL-8, and a significant relationship with pulmonary fibrosis in the patients, hence the role of BAL fluid cytokines in ILD pathophysiology." (PMID 37670355, 2023). "Several studies indicate that type 2 cytokines (IL-4 and IL-13) are profibrotic and stimulate type 1 collagen production by fibroblasts in pulmonary fibrosis." (PMID 36976645, 2023). "The Jak−STAT pathway is activated by several cytokines, such as IL-6, IL-4, IL-13, and TGF-β, which are implicated in the pathogenicity of pulmonary fibrosis." (PMID 36556326, 2022).
pulmonary fibrosis (continued). "Th2 cytokines, such as transforming growth factor (TGF)-β, interleukin (IL)-4, and IL-13, enhance the development of pulmonary fibrosis by activating fibroblast proliferation and collagen production." (PMID 35606782, 2022). "TH2 cytokines, in particular IL-4 and IL-13, have also a role in the differentiation of M2 macrophages, that in turn have a role in the development of pulmonary fibrosis through the secretion of TGF-β." (PMID 35386702, 2022). "In the post-irradiation lung fibrosis model, IL-4 production by macrophages exacerbated the fibrotic process, while in the bleomycin model, blockade of IL-4 reduced fibrosis." (PMID 36232756, 2022). "In summary, we first elucidated the role of Th9 cells in promoting pulmonary fibrosis through the secretion of IL-9 and IL-4." (PMID 34831433, 2021). "Our previous work has depicted the effector mechanism of IL-4/IL-13 signaling in the pathogenesis of pulmonary fibrosis and the upregulation of IL-31RA via the IL-4Rα/STAT6 signaling axis." (PMID 33815402, 2021). "One report suggests that SSc patients with lung fibrosis had higher IL4 production by peripheral blood lymphocytes." (PMID 33407866, 2021). "As an archetypal type-2 cytokine, interleukin 4 (IL-4) has been reported function as a pro-fibrotic cytokine and significantly elevated in idiopathic pulmonary fibrosis." (PMID 34711217, 2021). "Another study using IL-6 gene silencing showed that, in induced lung fibrosis, IL-6 played an important role in the regulation of the expression of Th2 cytokines (IL-4 and IL-5)." (PMID 34941770, 2021). "Both IL-4 and IL-3 are related cytokines that regulate many aspects of inflammation and have been reported to involve into the inflammatory responses of pulmonary fibrosis." (PMID 34711217, 2021). "Previous studies have identified important roles for Th2 T cell-derived IL-4 and/or IL-13 in the development of pulmonary fibrosis and other fibrotic diseases." (PMID 33815402, 2021). "While IL-4 has been associated with idiopathic pulmonary fibrosis (IPF), hepatic fibrosis and cardiac fibrosis, little is known about the role of IL-4 in the development of intestinal fibrosis." (PMID 34737752, 2021). "Both IL-4 and IL-13 are main type 2 cytokines produced by T helper 2 cells that play a critical role in pulmonary fibrosis." (PMID 34461906, 2021). "T-helper (Th) 1 secretes IFN-γ to reduce pulmonary fibrosis, whereas Th2 cytokines IL-4, IL-5, and IL-13 stimulate fibroblast proliferation, collagen production, and fibroblast activation." (PMID 33647885, 2021). "In AECs from both a BLM-induced fibrosis mouse model and pulmonary fibrosis patients, IL-4 and IL-13 mediate their fibrotic effect by binding to the receptor and activating JAK1." (PMID 34207510, 2021). "A subsequent manuscript describing roles for HIMF (FIZZ1) found that pulmonary fibrosis was a result of HIMF-regulated Th2-mediated mechanisms likely via IL-4 an IL-13 since HIMF expression was significantly decreased in IL-4 and IL-13 knockout mice." (PMID 33800244, 2021). "Of note, serum IL-31 levels positively correlated with the severity of skin and lung fibrosis and serum levels of IL-4, IL-6, and IL-13, which suggests the association of IL-31 with fibrosis and Th2 immune responses in SSc." (PMID 34642338, 2021). "Congruently, overexpression of GATA3, a transcription factor implicated in TH2 differentiation leads to augmented lung collagen deposition while animals in which IL-4 and IL-13 has been modulated, are protected from bleomycin-induced lung fibrosis." (PMID 34093523, 2021). "An elevated IL-4 has been reported in bronchoalveolar lavage fluid (BALF) from patients with pulmonary fibrosis." (PMID 34831433, 2021). "IL-4 and IL-13 are related to ILDs and are required for the maintenance of pulmonary fibrosis, modulating the abnormal activation of lung fibroblast." (PMID 34207510, 2021).
pulmonary fibrosis (continued). "CD103high Tregs can constrain lung fibrosis induced by CD103low tissue-resident pathogenic CD4+ T cells with higher production of effector cytokines, such as IL-4, IL-5, IL-13, IL-17A, and IFN-γ." (PMID 34488453, 2021). "Reducing the ratio of IFN-γ/IL-4 is beneficial to the occurrence and development of pulmonary fibrosis, while increasing the ratio of IFN-γ/IL-4 can alleviate pulmonary fibrosis." (PMID 32863857, 2020). "Inflammatory cytokines are important factors in radiation-induced lung fibrosis, and we checked the level of IL-4 and IFN-γ in BALF." (PMID 30988282, 2019). "DHP mainly regulated pulmonary fibrosis-related inflammatory genes and signaling pathways, such as IL1β, IL4, IL5, IL6, TGFβ1, and TNFα." (PMID 31105564, 2019). "More importantly, TB also causes extensive pulmonary fibrosis, which is associated with the production of TGF-Β, IL-4, and IL-1322,23." (PMID 30718463, 2019). "A molecular network linking macrophage activation, eosinophil recruitment and pulmonary fibrosis was generated using the transcriptional profiles, highlighting a central role of IL-13 and IL-4 in pathogenesis and cell recruitment/activation." (PMID 31469835, 2019). "Our findings are consistent with Wu's study of INF-γ dominance (Th1 cytokine) in pigeon breeder's lung patients at the acute/sub-acute stage and IL-4 dominance (Th2 cytokine) at the chronic stage after pulmonary fibrosis occurred." (PMID 35541981, 2018). "On the other side, expression of IGF-1 is inhibited by Th1 cytokine IFN-γ and induced by Th2 cytokines IL-4 and IL-13, while pulmonary fibrosis is a typical Th2 response that IL-4 and IL-13 predominate." (PMID 30018981, 2018). "After LPS induction, an increase in IL-4 content in BALF at 24 h and IL-4 expression was found to be correlated with the deposition of extracellular matrix and lung fibrosis." (PMID 30200495, 2018). "IL-4 limits the early recruitment of T lymphocytes and the chronic stimulation of fibrosis in a model of bleomycin-induced pulmonary fibrosis." (PMID 29772024, 2018). "A previous study has shown that reduction of IL-4- and IL-13-responsive macrophages and mononuclear cells using IL-13-Pseudomonas exotoxin A fusion protein attenuates bleomycin-induced lung fibrosis in mouse models." (PMID 29038604, 2017). "Further, they showed a substantial IL-4 production by macrophages during development of post-irradiation lung fibrosis." (PMID 28512460, 2017). "IL-4 as a pro-fibrotic cytokine is elevated in radiation-induced pneumonitis and pulmonary fibrosis, as well as in liver fibrosis." (PMID 29160801, 2017). "Although IL-13 contributes to pulmonary fibrosis, lung tissue levels of pro-allergic cytokines such as IL-4 and IL-13 were very low in all groups (<0.5 pg/mg), and IL-5 did not have consistent time- or concentration-dependent responses (data not shown)." (PMID 27083413, 2016). "Patients with pulmonary fibrosis from chronic hypersensitivity pneumonitis exhibit a predominantly Th2 pattern within the interstitial compartment of their lungs characterized by IL-4 and IL-5 activity." (PMID 25944985, 2015). "STAT6 also lies downstream of IL-4 and IL-13, which exhibit increased levels in human airway inflammatory diseases and are believed to play key roles in progression of pulmonary fibrosis." (PMID 25944985, 2015). "Interleukin-4 (IL-4) is a Th2 cytokine and has been found to take part in the pathogenesis of fibrosis in the ‘bleomycin model,’ as well as in idiopathic pulmonary fibrosis (IPF) patients." (PMID 23721656, 2013). "Mice over-expressing the Th2 cytokines IL-4 or IL-13 in their lungs exhibit features of COPD and pulmonary fibrosis in association with adenosine elevations." (PMID 20169073, 2010). "There are several evidences supporting that silica-induced lung fibrosis is correlated with markers of a Th2-like response such as increased IL-4 levels." (PMID 21072213, 2010).
pulmonary fibrosis (continued). "Based on these observations, they suggested that IL-4/IL-13-induced Retnla was playing a direct role in myofibroblast differentiation and in the pathogenesis of pulmonary fibrosis." (PMID 19381262, 2009). "The TF-mRNA‒miRNA network analysis indicated that miR-200c-3p may target IL4 and contribute to the development of pulmonary fibrosis." (PMID 41481554, 2026). "respiratory disease dataset, we observed significant enrichment of IFNγ signatures in cystic fibrosis and COVID‐19 infection, IL‐33 in COPD and COVID‐19, IL‐4 + IL‐13 in pneumonia, and TGFβ signatures in pulmonary fibrosis (PF) and chronic rhinosinusitis (CRS)." (PMID 40926620, 2025). "Obese Nod2−/− mice had higher inflammatory cell infiltration in the bronchial alveolar lavage (BAL) and lungs, pulmonary fibrosis, mucus levels, hypertrophy and hyperplasia of goblet cells, M2 alveolar macrophage infiltration, interleukin-4 (IL-4), IL-5, IL-6, and lower CXCL1 and IL-22." (PMID 39507249, 2024). "In this study, we verified that diazepam can effectively inhibit inflammation in pulmonary fibrosis; specifically, diazepam can effectively inhibit the expression of the inflammatory cytokines IL-4, IL-6 and TNF-α and effectively alleviate the occurrence of pulmonary fibrosis." (PMID 38875245, 2024). "In addition to IL-4 and IL-13, it has been observed that IL-5 can also play a role in tissue remodeling in several diseases including pulmonary fibrosis." (PMID 37063828, 2023). "Given the fact that Th2 cytokines serve as essential regulators for generating and maintaining a fibrotic microenvironment in the late stage of pulmonary fibrosis, we stimulated macrophages with cytokines IL-4 and IL-13 together, to stimulate the Th2 microenvironment." (PMID 37523510, 2023). "Conversely, miR-142-5p overexpression seem to contribute to the establishment of chronic inflammatory diseases, sustaining profibrogenic properties of macrophages induced by IL-4 and IL-13 and showing upregulation in macrophages from tissue samples of patients with idiopathic pulmonary fibrosis." (PMID 36972298, 2023). "Moreover, lung biopsies from patients suffering from idiopathic pulmonary fibrosis also exhibited elevated levels of IL-13 and IL-4." (PMID 36982747, 2023). "Moreover, IL-4 concentrations were increased in the bronchoalveolar lavage fluids from patients with idiopathic pulmonary fibrosis." (PMID 37063828, 2023). "In this study, LPS/IL-4-induced macrophages showed upregulation of Arg1 compared to M2 macrophages, despite expression of iNOS being very low, suggesting that both M2 and LPS/IL-4-induced macrophages may be involved in the pathogenesis of pulmonary fibrosis." (PMID 37180123, 2023). "In 2018, news studies showed that S1PR2 might also affect pulmonary fibrosis on a transcriptional level; S1PR2 deletion reduced the expression of profibrotic cytokines such as IL-13 and IL-4 in bleomycin-induced pulmonary fibrosis." (PMID 37371823, 2023). "Given that lung fibrosis in mice has been linked to increased polarization of macrophages to an IL-4-induced “M2a” phenotype, the effect of the SIK2 kinase-inactive knockin was tested on IL-4 and LPS-induced markers on macrophages." (PMID 36309093, 2022). "Periostin, induced by the Th2 cytokines IL-4 and IL-13, has been reported to be involved in pulmonary fibrosis with crosstalk of transforming growth factor-β21,22, and serum periostin could be a good predictor of decreased lung function and poor prognosis." (PMID 36380088, 2022). "IL-4 and IL-5 were also discovered in the promotion of pulmonary fibrosis." (PMID 35910226, 2022). "In contrast, in a silica-induced murine model of lung fibrosis, the neutralization of immunosuppressive activity of Tregs reportedly led to the accumulation of effector T-cells and contributed to the worsening of fibrosis via IL-4 secretion." (PMID 36301948, 2022).